ACE (angiotensin I converting enzyme)
Diseases named in the same sentence as ACE in open-access papers (continued):
Sharing a sentence is not in itself a finding about the gene and the disease.
dementia (continued). "A number of AT1 receptor antagonists, capable of penetrating the BBB, are now available with new ones in clinical trials; however, the vast majority of clinical studies concerned with the use of antihypertensive agents to treat dementia have focused on ACE inhibitors and diuretics." (PMID 24298267, 2013). "Both APOE and ACE variants also affect behavior and the modification of behavioral changes (mood and anxiety) in dementia after nonpsychotropic pharmacological treatment." (PMID 22482072, 2012). "(x) APOE may also interact with PSEN1, ACE, A2M, and other genes to regulate the effect of drugs on cognition and behavioral changes in dementia." (PMID 22482072, 2012). "Thus, ACE inhibitors and angiotensin receptor blockers (ARBs) may reduce the pathogenesis of dementia and cognitive impairment by reducing neuronal inflammation and oxidative stress." (PMID 39828641, 2025). "Thus, ACE inhibitors and ARBs may reduce the pathogenesis of dementia and cognitive impairment by reducing neuronal inflammation and oxidative stress." (PMID 39828641, 2025). "A combination of calcium channel blocker, angiotensin-converting enzyme (ACE) inhibitor and diuretic was found to have reduced the incidence of dementia in AD cases after two and four years of follow-up by 50% and 55% respectively." (PMID 27557144, 2016). "Examination of the highlighted keywords revealed the commonality between HF and dementia, namely IL6, ACE, APOE, APP, ADIPOQ, LEP, and NPPB, suggesting that these proteins may link the two pathologies." (PMID 40699836, 2025). "The analysis included 4,830 subjects who did not have dementia at baseline, and for whom information was available on ApoE genotype, ACE inhibitor use, and the follow-up diagnoses on AD." (PMID 23948883, 2013). "Epidemiological studies and clinical trials have shown that pharmacological modulation of the RAS using ACE inhibitors (ACEIs) and AT1R antagonists (ARA-II) not only controls blood pressure but also offers neuroprotective benefits, reducing the incidence of cognitive decline and dementia." (PMID 40868980, 2025). "Evidence from large epidemiological and clinical studies indicate that some cRAS-targeting anti-hypertensives, including ACE1 inhibitors (ACE-Is) and AT1R receptor blockers (ARBs), reduce the incidence of AD, and can prolong the conversion to MCI and delay the onset of dementia." (PMID 31982938, 2020). "Several studies showed protective functions of RAS blockade—by ACE inhibitors or AT1R antagonists—against cognitive decline and dementia (in non-PD patients), or the progression of PD." (PMID 34302265, 2021).
Insulin resistance (79 papers, 2008 to 2026). Increased resistance towards insulin, that is, diminished effectiveness of insulin in reducing blood glucose levels. "It’s well understood that COVID-19 affects the hemostasis of glucose by different mechanisms which include insulin resistance and insulin insufficiency, as well as the role of ACE polymorphism which strongly related to DM." (PMID 39304825, 2024). "In the context of T2D, angiotensin II, produced from angiotensin I by ACE, has been implicated to play a role in the development of insulin resistance." (PMID 30744071, 2019). "In our study population, 15%, 25% and 33% were treated with an ACE inhibitor, calcium channel blocker and diuretic, respectively, and these variables were associated with our measures of insulin resistance (P<0.1)." (PMID 21901158, 2011). "Additionally, some research have shown that the D allele of the ACE gene may be linked to acanthosis and a greater risk of insulin resistance in PCOS patients." (PMID 36619582, 2022). "As part of the RAS, ACE converts angiotensin I to the potent vasoconstrictor angiotensin II, which can lead to increased oxidative stress and inflammation, exacerbating insulin resistance and beta cell dysfunction." (PMID 39195477, 2024). "The M235T polymorphism of the angiotensinogen gene is related to insulin resistance in PCOS patients, and the genotype of ACE is related to the occurrence and development of PCOS women." (PMID 38195648, 2024). "In general, several therapeutic agents can improve endothelial vasodilator function and insulin resistance: pioglitazone, metformin, angiotensin-converting enzyme (ACE) inhibitors and angiotensin II-receptor antagonists (AT1-receptor blockers)." (PMID 36296702, 2022). "On this basis, we will summarize the available evidence to compare ACE inhibitors with ARBs on the effect of insulin resistance in hypertensive patients." (PMID 32541513, 2020). "The positive effects of ACE inhibitors on lipid profile and insulin resistance have also been observed in obese pediatric patients with MetS and essential hypertension." (PMID 32235782, 2020). "Due to the interplay of pathophysiology between the RAS and insulin resistance, there is a great potential for ACE inhibitors to alleviate other complications of the MetS." (PMID 32235782, 2020). "In parallel, there is a downregulation of ACE-2-(A1-7)-Mas axis and thus, diminished anti-inflammatory effects and protection against pancreatitis and insulin resistance." (PMID 33123550, 2020). "Due to the close relationship between the ACE and KKS systems, ACE inhibitors and B2R agonists such as BK have been suggested to represent new ways of targeting insulin resistance." (PMID 29462993, 2018). "Despite presenting with no biological activity, once broken down to angiotensin II (AngII) via a consecutive action of renin and ACE, it can induce insulin resistance via a cross-talk mechanism between insulin and AngII signaling cascade." (PMID 26682227, 2016). "The purpose of the current study was to investigate the effects of the use of ACE inhibitors on lipid profile, insulin resistance, and in turn, on development of MS in obese pediatric patients with MS and essential hypertension." (PMID 24072084, 2013). "Nevertheless, we were able to show the benefits of using ACE inhibitors on the most important criteria of MS, namely, hypertriglyceridemia and insulin resistance." (PMID 24072084, 2013). "The activation of the classical angiotensin (Ang)-converting enzyme (ACE)/Ang II/Ang II type 1 receptor (AT1R) axis of the renin-angiotensin system (RAS) has been associated with islet dysfunction and insulin resistance." (PMID 23942780, 2013). "In SD rats maintained on a fructose-rich diet, which promotes the development of hypertension and insulin resistance, the administration of the ACE inhibitor or AT1R blocker (Olmesartan) significantly reduced blood pressure, improved insulin sensitivity, and reduced adipocyte size." (PMID 38279313, 2024).
Insulin resistance (continued). "Furthermore, a recent study has shown that tripeptides with ACE inhibitory activity improved insulin resistance in rat-derived L6 skeletal muscle cells, at least partially via reduced AGTR-1 expression and attenuating reactive oxygen species (ROS) in L6 cells." (PMID 36112580, 2022). "Indeed, experimental evidence indicates that in animal models of insulin resistance, ACE inhibitors ameliorate the insulin resistance." (PMID 34685777, 2021). "ACE is an enzyme that hydrolyzes angiotensin I to produce angiotensin II, which elevates blood pressure, promotes inflammation, and plays a role in the development of insulin resistance." (PMID 30744071, 2019). "It is evident that apart from their antihypertensive effect, both ARBs and ACE inhibitors may exert beneficial effects on lipid and carbohydrate metabolism and insulin resistance, which may explain the possible protective role of these medications partially." (PMID 30425742, 2018). "Thus, we concluded that HOMA-IR was increased in the NAFLD group as an indicator of insulin resistance, the ACE levels were also increased, and so, it was a significant factor in terms of adiposity and progression to fibrosis." (PMID 29201746, 2016). "But insulin resistance was not a significant factor in the subgroups in terms of ACE gene polymorphism." (PMID 29201746, 2016). "Furthermore, the miR-143/145 cluster has been implicated in insulin resistance and the development of T2DM and has also been demonstrated to inhibit angiotensin II formation, by targeting angiotensin-converting enzyme (ACE) thus, impairing wound healing." (PMID 25268390, 2014). "However, it is known that during this transition insulin resistance develops, cardiac glucose uptake down-regulates, angiotensin-converting enzyme (ACE) levels increase, and the renin-angiotensin aldosterone system (RAAS) becomes hyperactivated." (PMID 20678234, 2010). "Moreover, insulin resistance is associated with the renin-angiotensin system (RAS), in which the initial action of renin cleaves angiotensinogen to angiotensin I (ANG I), then ANG I converts to ANG II by the angiotensin converting enzyme (ACE)." (PMID 36112580, 2022). "Interestingly, an upregulation of ACE-Ang-II-AT1R axis leading to pro-inflammatory effects, insulin secretory defects and increased insulin resistance was demonstrated in people with underlying lipid and other metabolic disturbances, such as in the case of metabolic syndrome and diabetes." (PMID 33123550, 2020). "Various management guidelines recommend ARBs and ACE inhibitors as the first-line antihypertensive treatments for such patients based on the beneficial reduction in the frequency of cardiovascular events and mortality attributed to the insulin resistance-improving effects of ARBs and ACEs." (PMID 30943275, 2019). "In addition, I allele of ACE I/D polymorphism was found to be associated with increased indexes of insulin resistance in nondiabetic Caucasians and Africans." (PMID 26491214, 2015). "Whether this effect outweighs the inhibition of the Ang II-dependent effects remains to be determined, but if this is indeed the case it would suggest that AT1 receptor antagonists would be superior to ACE inhibitors in preventing or reducing insulin resistance." (PMID 20383279, 2010). "Physiological assessments included body weight, fasting glucose, insulin, homeostatic model assessment for insulin resistance (HOMA-IR), serum lipids, sex hormones, angiotensin-converting enzyme (ACE) activity, and histological evaluation of cardiac tissue." (PMID 41464892, 2025). "Data analysis demonstrated that PMG has a positive effect on body weight gain, and lipid and glucose values, as well as improving Homeostasis Model Assessment of Insulin Resistance (HOMA-IR) and Angiotensin-Converting Enzyme (ACE) levels." (PMID 37047080, 2023).
Insulin resistance (continued). "Previous studies have shown inconsistent outcomes in the efficacy of angiotensin-converting enzyme inhibitors (ACE inhibitors) and angiotensin receptor blockers (ARBs) on insulin resistance (IR)." (PMID 32541513, 2020). "This axis induces beneficial effects in hypertension, glucose intolerance, and insulin resistance (IR), and it acts in a counter-regulatory way to another important RAS axis, ACE/Ang II/AT1 receptor." (PMID 31396301, 2019). "An ACE inhibitory tripeptide, IRW (Ile-Arg-Trp), which is derived from egg white ovotransferrin, has been indicated to be beneficial against insulin resistance." (PMID 30744071, 2019). "An excess of ANGII induces insulin resistance and impairs glucose homeostasis through the classical RAS pathway by modulating the angiotensin-converting enzyme/ANGII/angiotensin II type I receptor (ACE/ANGII/AT1R) axis." (PMID 29695972, 2018). "Notably, milk proteins also possess bioactive peptides that have ACE-inhibitory properties, and the ACE product angiotensin II enhances adipocyte lipid storage, promotes inflammation via activation of the NFκB pathway, and stimulates ROS-mediated insulin resistance." (PMID 22269778, 2012). "Increasing evidence from in vitro studies and animal models using ACE inhibitors (ACEI), Ang II AT1 receptor antagonists (ARB) and more recently renin inhibitors (RI), indicates that Ang II is involved in insulin resistance." (PMID 20383279, 2010). "The ACE2–Ang (angiotensin) 1–7–Mas axis of skeletal muscle plays a role in preventing the development of insulin resistance or muscle wasting, which is a major pathway to counteract the ACE (angiotensin converting enzyme)–Ang II–AT1 (angiotensin type 1 receptor) axis." (PMID 36514781, 2022). "Cordyceps may play a crucial role in the treatment of DN by targeting TNF, MAPK1, EGFR, ACE, and CASP3 signaling and involved in the inflammatory response, apoptosis, oxidative stress, and insulin resistance." (PMID 33628839, 2021). "The purpose of the present study was to determine whether hypertension, insulin resistance, and renal dysfunction in DSS rats fed a high-salt diet could be attenuated by the exenatide analogue, AC3174, alone or in combination with the ACE inhibitor captopril." (PMID 20678234, 2010). "The potential benefits of optimal egg-derived protein might be due to its metabolites, such as alpha-glucosidase inhibitory peptides, ACE inhibitory peptides, DPP-4 inhibitory peptides, which showed effects on the improvement of glucose tolerance, postprandial hyperglycemia, and insulin resistance." (PMID 35022027, 2022). "Other investigations have verified that, despite the ACE gene polymorphism not being linked to the pathophysiology of PCOS, it may be strongly linked to a number of metabolic diseases such insulin resistance, hyperlipidemia, and hyperandrogenemia." (PMID 36619582, 2022). "In brief, these relationships demonstrated that angiotensinogen and ACE were found in adipocytes in obese humans, thereby raising the possibility that ANG II was produced locally and could exert local effects contributing to insulin resistance." (PMID 29462993, 2018).
asthma (74 papers, 2006 to 2025). "Three AE comorbidities remained in the model, COPD, asthma and ACE inhibitor prescription – these were associated with a 59.1, 30.6 and 7.7 day increase in DI respectively." (PMID 39179794, 2024). "This study was conducted to determine if ACE I/D polymorphism was associated with a clinical phenotype of DSGA or ESGA in asthma patients." (PMID 19525331, 2011). "Conversely, a significant association of the ACE I/D polymorphism with asthma was reported in asthma patients from the Czech Republic." (PMID 19525331, 2011). "Polymorphisms in the ACE gene were implicated in risk of asthma and AERD." (PMID 30254660, 2018). "ADAM33, FcεRIβ, RANTES, TNF-α, ACE, β2-AR, IL-4R and IL-13 genes could be proposed as asthma susceptible genes in Chinese population." (PMID 20868478, 2010). "Elevated ACE levels may be associated with an increased risk for different cardiovascular or respiratory diseases, including asthma." (PMID 20011602, 2009). "In the model where the comorbidities were considered individually, we found significant increases in DI for three of our suggested AE conditions, ie, COPD, asthma and ACE inhibitor prescription." (PMID 39179794, 2024). "Cox proportional hazards modeling for time to death demonstrated a significantly high ratio for COPD/Asthma, and favorable effects on outcomes for pre-admission ACE inhibitors and ARBs." (PMID 33461499, 2021). "Significant positive correlations were established between increasing age with ILD, use of ACE-Inhibitors and CCF, as well as younger age with cough variant asthma and allergic rhinitis." (PMID 32292434, 2020). "The angiotensin-converting enzyme (ACE), a key enzyme of the renin angiotensin system, is mainly expressed in the lung and plays an important role in the pathogenesis of asthma." (PMID 30254660, 2018). "The AAAAI/ACAAI Guidelines describe patient-specific risk factors such as asthma, CVD, and mastocytosis, and concurrent beta-blocker and ACE-inhibitor use." (PMID 24920969, 2014). "The angiotensin I converting enzyme (ACE) inactivates bradykinin and tachykinins such as neurokinin A and substance P, which play important roles in asthma." (PMID 19525331, 2011). "According to the available medical literature, asthma patients in France are characterized by a higher prevalence of the ACE D/D genotype." (PMID 19525331, 2011). "To accomplish this, we classified asthma patients into DSGA or ESGA categories and then analyzed the patients for the presence of ACE I/D polymorphism using polymerase chain reaction (PCR)." (PMID 19525331, 2011). "Up to date, we first found that ADAM33 T1-C/T, ACE D/I, IL-13 -1923C/T, RANTES -28C/G and IL-13 -2044A/G polymorphisms were associated with risk of asthma in Chinese population by using meta-analyzes." (PMID 20868478, 2010). "Among them, seven polymorphisms (ADAM33 T1-C/T, ACE D/I, FcεRIβ -6843G/A, IL-13 -1923C/T, IL-13 -2044A/G, RANTES -28C/G and TNF-α -308G/A) were statistically associated with increased risk of asthma." (PMID 20868478, 2010). "Because the fixed-effect model is more precise than random effect model, the strength of evidence of ADAM33 T1-C/T, ACE D/I, IL-13 -1923C/T, RANTES -28C/G, as risk factors for asthma was greater than that of FcεRIβ -6843G/A, IL-13 -2044A/G and TNF-α -308G/A." (PMID 20868478, 2010). "Patients with chronic cough should have a history taken and physical examination carried out to evaluate common causes of cough (asthma, sinusitis, GERD, ACE inhibitors), as well as chest radiograph." (PMID 19641641, 2009). "BK is another substrate for ACE, perhaps the “best” with the highest Km, and is a potent vasodilator that induces cough and bronchoconstriction in subjects with asthma." (PMID 20011602, 2009). "Perhaps decreased ACE tissue levels increase local tissue concentration of BK and so promote asthma symptoms." (PMID 20011602, 2009).